EGFR (epidermal growth factor receptor)
Diseases named in the same sentence as EGFR in open-access papers (continued):
Sharing a sentence is not in itself a finding about the gene and the disease.
breast carcinoma (continued). "The expression of EGFR was alongside the expression of other prominent breast cancer biomarkers such as the androgen receptor and Ki67 protein (the cellular marker for cell proliferation), thus suggesting EGFR is another therapeutic target for breast cancer treatment." (PMID 31064156, 2019). "In this study, we examined the effects of combining ATX-101 with an EGFR/HER2/VEGFR inhibitor (AEE788) in vitro and in vivo in an orthotopic syngeneic HER2-/progesterone receptor - (PR-), estrogen receptor + (ER+)/EGFR+ mixed luminal/basal breast cancer mouse model." (PMID 31921382, 2019). "Cdc42 mainly functions as an EGFR-signaling regulator in breast cancer cell proliferation." (PMID 30754684, 2019). "Our group modified 111In-labelled anti-EGFR mAb nimotuzumab with 13-mer peptides CGYGPKKKRKVGG that harbour the SV-40 large T-antigen-derived nuclear localisation sequence (NLS; italicised) and studied the cytotoxicity of these radioimmunoconjugates towards EGFR-positive breast cancer cells." (PMID 31659527, 2019). "In breast cancer, oestrogen was responsible for maintaining low levels of EGFR expression." (PMID 31315563, 2019). "Besides that, inhibition of HER-2 signalling by specific human epidermal growth receptor 1/HER-2 (EGFR/HER-2) kinase inhibitor lapatinib synergistically enhanced the anti-cancer effects of honokiol in HER-2 over-expressed breast cancer cells." (PMID 31877856, 2019). "EGFR-specific CAR-T cells could be derived either from the patients’ own T cells or from iPSC cells and then injected either into breast tumors or intravenously to treat EGFR-positive breast cancer patients." (PMID 31804974, 2019). "Furthermore, the expression of EGFR was also decreased, supporting that the EGFR‐importin α5 signalling pathway is involved in β‐elemene inhibition of breast cancer metastasis." (PMID 31343107, 2019). "Another type of therapy is based on obtaining and using monoclonal antibodies (mAbs) to surface proteins highly expressed in cancer cells, such as CD20 in lymphoma (rituximab), HER2 in breast cancer (trastuzumab), and epidermal growth factor receptor (EGFR) in colon cancer (cetuximab)." (PMID 31921125, 2019). "Furthermore, overexpression of UCHL1 is consistent with a multi-drug resistance (MDR) phenotype in breast cancer cells and is believed to function through EGFR and MAPK29,30." (PMID 30914750, 2019). "It was found that epidermal growth factor receptor- (EGFR-) positive breast cancer was more prevalent in Asian women diagnosed than Western women and high expression of EGFR oncoprotein was associated with advanced stages of breast cancer." (PMID 31485222, 2019). "AJAP1/EGFR KD group improved the tumor growth and weight, β-catenin nuclear expression and the expressions of C-myc and CyclinD1 compared with the other two groups isolated from the breast cancer cell-inoculated nude mice." (PMID 31171012, 2019). "However, it has been well-defined that the aberrant tyrosine kinase activity by EGFR has a close relation with tumorigenesis in a variety of cancer types such as lung, colon, and breast cancers." (PMID 30957572, 2019). "Similarly, peptide 1 is a good candidate peptide for breast cancer targeting as it binds EGFR, and can be engineered for proteolytically stability and specific targeting of TNBC cells." (PMID 30804365, 2019). "Taken along with our previous results, HDAC3 phosphorylation by EGFR–c-Src may be involved in regulating the invasiveness of breast cancer cells through the modulation of its enzymatic activity." (PMID 31430896, 2019). "However, despite these findings, the effects on transcription following long term EGF stimulation of EGFR (> 20 min) and its underlying chromatin basis remains unexplored in HER2+ breast cancer cells." (PMID 30736768, 2019).
breast carcinoma (continued). "In addition to interacting with EGFR, Cdc42 has many other means of advancing breast cancer cell growth." (PMID 30754684, 2019). "Furthermore, its cognate receptor EGFR is over-expressed in breast cancer cells and is correlated with poor prognosis." (PMID 31428691, 2019). "However, c-Cbl is often compromised in breast cancer and the upregulation of Cdc42 activity is considered to impair c-Cbl activation, thus inhibiting EGFR degradation." (PMID 30754684, 2019). "In MDA-MB-231 human breast cancer cells, honokiol downregulated the expression and phosphorylation of c-Src, epidermal growth factor receptor (EGFR), and Akt, and consequently led to the inactivation of mTOR and its downstream signal molecules including 4E-binding protein (4E-BP) and p70 S6 kinase." (PMID 31877856, 2019). "Our findings that BIBX1382, gefitinib and LY294002 reduced EGFR-mediated FDG uptake might also have relevance on the therapeutic effects of newer drugs for breast cancer that target EGFR or the PI3K pathway." (PMID 31532771, 2019). "EGFR is an important driver gene involved in the progression of breast tumors to advanced forms, and its altered expression is observed in a number of breast cancer cases." (PMID 30978274, 2019). "Lapatinib (LP) is an FDA-approved dual EGFR/HER2 inhibitor for HER2-amplified breast cancer." (PMID 30781364, 2019). "Due to the function of EGFL9 as an activator of cMET, EGFL9 expression may be a predictive marker for resistance to EGFR-targeted therapy in some breast cancer patients." (PMID 31695034, 2019). "A shorter time period was used for estimating the doses from 111In-DTPA-human epidermal growth factor (111In-DTPA-hEGF) in 15 patients with EGFR positive breast cancer using whole body planar images acquired at 1, 4–6, 24 and 72 h p.i., since radiopeptides are eliminated more rapidly than mAbs." (PMID 31659527, 2019). "However, surface tyrosine kinase receptors belonging to the EGFR/ErbB family (which is named for a homologous erythroblastic leukemia viral oncogene) are very often found upregulated in breast cancers." (PMID 31756933, 2019). "Of the several therapeutic antibodies used in cancer treatment, some are used in solid tumours, targeting specific antigens such as the epidermal growth factor receptor (EGFR) found in colorectal cancer, or the human epidermal growth factor 2 (HER2) associated with breast cancer." (PMID 31817406, 2019). "Besides, ectopic expression of EYA2 promoted proliferation of breast cancer cells accompanied with the up-regulation of EGFR, cyclin E, and PCNA." (PMID 30761270, 2019). "Similarly, systematically injected exosome carrying specific EGFR peptides fused to platelet-derived growth factor receptors (PDGF-R) delivered let-7a miRNA in EGFR-expressing xenograft breast cancer tissue in RAG2(−/−) mice with a therapeutic response." (PMID 30634425, 2019). "The goal of the current study is to evaluate the in vivo fate of human epidermal factor receptor 2 (HER2) and epidermal growth factor receptor (EGFR) dual-targeted PTX+EVER-loaded NPs (Dual-NPs) in an MDA-MB-231-H2N breast cancer (BC) tumor-bearing mouse model." (PMID 31146485, 2019). "By using molecular modeling and in vitro studies, BBR significantly reduced EGFR and AKT phosphorylation and may be a useful alternative to lapatinib, an EGFR inhibitor which can cause acquired drug resistance in breast cancer patients." (PMID 31208348, 2019). "Breast cancer patients are stratified into different molecular subtypes with respect to the expression of nuclear hormone receptors (i.e., estrogen receptor (ER) and progesterone receptor (PR), and epidermal growth factor receptor (Her2)." (PMID 31883527, 2019).
breast carcinoma (continued). "However, PLGA-PEG NPs conjugated with EGFR-targeting GE11 peptide for breast cancer therapy prolonged the half-life to ~6 h." (PMID 31197096, 2019). "In pathological settings, such as lung and breast cancer, the EGFR is a driver of tumourigenesis." (PMID 30659329, 2019). "Interestingly, up-regulating GPR30 was also found in high-risk endometrial cancer patients with lower survival rates and in tamoxifen-resistant breast cancer cells through the EGFR/ERK transduction pathway." (PMID 31737560, 2019). "In addition, ERβ decreased basal-like breast cancer cell invasion by promoting degradation of epidermal growth factor receptor (EGFR)." (PMID 31412908, 2019). "In particular, c-Src and EGFR are overexpressed in ~70% of breast cancer cases." (PMID 31430896, 2019). "Furthermore, we investigated the relationships between PN-1 and EGFR in breast cancer cell lines and tissues." (PMID 31501409, 2019). "In addition, clinical breast cancer biopsy-based immunostaining assay demonstrated that CL-4RNV616 had a comparable detection efficacy for EGFR positive breast cancer with commonly used commercial antibodies." (PMID 31546749, 2019). "MDA-MB-468 is a breast cancer cell line that expresses high levels of EGFR and Eps8." (PMID 31118055, 2019). "Therefore, a better understanding of the mechanism and signaling pathways through which EGFR influences breast cancer cell glucose metabolism would benefit these endeavors." (PMID 31532771, 2019). "A previous study from our laboratory demonstrated that HER2+ breast cancer cells resistant to trastuzumab had higher levels of EGFR relative to controls, which we hypothesized could amplify downstream signaling and enhance migration." (PMID 30736768, 2019). "The main therapeutic targets for breast cancer taken for the study were ERα, PR, EGFR, and mTOR." (PMID 31673107, 2019). "Interestingly it has been shown that EGFR expression downregulates hsa-miR-338-3p expression, matching our observations on the breast cancer cell lines." (PMID 31063487, 2019). "EGFR is an established therapeutic target in the treatment of breast cancer." (PMID 31408580, 2019). "Therefore, TGF‐β not only transactivates the EGFR signaling but also promotes the migration and invasion abilities of breast cancer cells." (PMID 29215776, 2018). "KLF10 is an anti-metastasis gene that significantly prevents breast cancer cell invasion, suppresses mammary tumorigenesis and decreases lung metastasis by inhibition of EGFR (epidermal growth factor receptor) gene transcription through the EGFR signaling pathway." (PMID 29799499, 2018). "Inhibition of the EGFR in Her2 amplified breast cancer cells induces a reduction of PTPIP51 phosphorylation at the Tyr176 residue accompanied by a formation of the Raf-1/14-3-3β/PTPIP51 interactome, thus proofing a normal regulation of MAPK-related interactions of PTPIP51." (PMID 30360441, 2018). "Trails of EGFR inhibitors in breast cancer, however, have been disappointing." (PMID 30356721, 2018). "Furthermore, ADAMTS9 inhibits the AKT pathway through suppressing EGFR and TGFβ1/TβR(I/II) in breast cancer cells." (PMID 29193730, 2018). "In order to further confirm that β-catenin nuclear accumulation was stimulated by EGFR signal in Akt1-impaired cells, we tested the effect of Gefitinib, an inhibitor of EGFR tyrosine kinase on the β-catenin nuclear accumulation in the breast cancer cells treated with Akt1 siRNA." (PMID 30445978, 2018). "MET expression correlates positively with EGFR expression in basal-type breast cancers." (PMID 30227653, 2018). "Then, we wonder whether the increased in EGFR total protein expression in Akt1 impaired breast cancer cells was dependent on its transcriptional regulation." (PMID 30445978, 2018). "In general, EGFR is considered to be a negative prognostic factor in patients with breast cancer and such an association has been shown in ours, as well as in other studies." (PMID 30521571, 2018).
breast carcinoma (continued). "lncRNA CYTOR regulates the breast cancer progression through EGFR dependent pathway." (PMID 29455658, 2018). "Higher activation of EGFR/HER2 might be the driving force in enriching CSC population in tamoxifen-resistant breast cancer." (PMID 29455658, 2018). "Knockdown of Akt1 induced sustained activation of EGFR in breast cancer cells." (PMID 30445978, 2018). "In addition, the overexpression of EGFR protein specific to TNBC (when compared with other subtypes of breast cancers) usually increase resistance of this type of cancer cells to conventional therapies." (PMID 29978332, 2018). "To investigate whether EGFR plays a vital role in TGF‐β‐induced enhancement of the migration and invasion abilities of breast cancer cells, we knocked down the expression of EGFR in MDA‐MB‐231 and T47D cells using two different siRNA." (PMID 29215776, 2018). "AnxA6 expression is reduced in breast cancer cells and when expressed terminates EGFR signaling." (PMID 29416802, 2018). "This fundamental change in response to EGF through breast cancer progression led us to address the hypothesis that pharmacological biasing of downstream signaling could reveal apoptotic EGFR signaling, even in early-stage breast cancer." (PMID 30250119, 2018). "In this study, the expression of TGF‐β and EGFR in breast cancer tissues was investigated." (PMID 29215776, 2018). "CA XII expression is seen in 75% of breast carcinomas associated with the estrogen receptor positive (ER+) and epidermal growth factor receptor negative (EGFR-) subtype." (PMID 29710858, 2018). "There are a number of liquid biopsy tests that have been approved by FDA so far, such as the breakthrough device from the Foundation Medicine company, approved at 2018; the cobas EGFR mutation test v2, approved for NSCLC in 2017; myRisk, approved for breast cancer in 2014." (PMID 30424330, 2018). "To investigate whether inhibition of PIKfyve is required for β-catenin nuclear accumulation via the prolonged activation of EGFR in breast cancer cells, we then treated MCF-7 and MDA-MB-231 cells with a PIKfyve specific inhibitor YM201636." (PMID 30445978, 2018). "Furthermore, circulating tumor cells “primed” for breast cancer brain metastases have a specific gene signature (HER2+/EGFR+/HPSE+/Notch1+)." (PMID 30515368, 2018). "In this section, we provide a more in-depth analysis of the four cancer-drug combinations on which most research has been done: Proteasome inhibitors for multiple myeloma, EGFR inhibitors for breast cancer, cisplatin for lung and ovarian cancer, and BRAF inhibitors for melanoma." (PMID 30456204, 2018). "Importantly, Snai2 is more expressed in basal-like breast cancer cells, which are often characterized by increased levels of EGFR, and a correlation exists between EGFR and Snai2 expression in several cancer types, among whom breast cancer." (PMID 29674627, 2018). "The TGF‐β‐induced EGFR expression was more strongly inhibited by the double suppression of Smad3 and Sp1 expression than by the single‐Sp1 or single‐Smad3 siRNA‐transfected breast cancer cells." (PMID 29215776, 2018). "The use of tumor-derived extracellular vesicles to deliver therapeutic miRNAs was recently reported, wherein the authors described the efficient delivery of the tumor suppressive miRNA let-7a to epidermal growth factor receptor (EGFR)-expressing breast cancer cells in vivo." (PMID 29419779, 2018). "Hence, the targeting of cIAP1 strongly reduces EGFR signaling with consequent inhibition of Snai2 expression, which is a well-known promoter of breast cancer cell aggressiveness." (PMID 29674627, 2018). "Human epidermal growth factor receptor HER3 (ErbB3), a cell membrane-associated protein encoded by the ERBB3 gene, is a promising target for cancer therapy, especially in HER2-positive (carrying ERBB2/HER2 gene amplification) breast carcinoma." (PMID 30367623, 2018).
breast carcinoma (continued). "Thus, consistent with the literature, we show that NDRG1 regulates the activation of EGFR and downstream kinases in breast cancer in response to progesterone." (PMID 30337371, 2018). "Finally, MUC1 can also promote EGFR-dependent cell motility and acinar branching of breast cancer cells through the upregulation of c-Met." (PMID 29464085, 2018). "In addition, we demonstrated, for the first time, that ADAMTS9 inhibits AKT signaling, through suppressing its upstream activators EGFR and TGFβ1/TβR(I/II) in breast cancer cells." (PMID 29193730, 2018). "However, the results revealed that knockdown of Akt1 in MCF-7 and MDA-MB-231 cells failed to promote the mRNA expression of EGFR, suggesting that additional target is contributing to the overexpression of EGFR in Akt1 impaired breast cancer cells." (PMID 30445978, 2018). "Indeed, in vivo and in vitro studies have strongly suggested that DCN blocks the growth and distant metastasis of breast cancer cells by down-regulating EGFR expression and interfering with the formation of EGFR/ErbB2 dimers." (PMID 29435195, 2018). "In addition, an increase in EGFR total protein expression was also observed in these Akt1 knockdown breast cancer cells." (PMID 30445978, 2018). "In this work, antibody-guided ANANAS were evaluated and quantitatively compared with direct ADCs for targeted drug delivery in breast cancer therapy using an anti-epidermal growth factor receptor (EGFR) antibody (cetuximab) as the targeting element and doxorubicin as the cytotoxic compound." (PMID 30287819, 2018). "Therefore, our data suggested that TGF‐β transactivates EGFR signaling by upregulating EGFR expression and facilitates breast cancer migration and invasion." (PMID 29215776, 2018). "To test the hypothesis, we first examined whether Akt1 inhibition could induce EGFR activation in breast cancer cells." (PMID 30445978, 2018). "Moreover, Tai report an EGFR-dependent β4 integrin/FAK complex that contributes to malignancy of breast cancer, indicating the interaction between EGFR and β4 integrin." (PMID 29618949, 2018). "Hence, our study suggested that TGF‐β transactivates EGFR signaling by upregulating the EGFR expression in breast cancer cells." (PMID 29215776, 2018). "Given that Akt1 inhibition promotes the activation of EGFR in breast cancer cells, we further examined whether the inhibitor of EGFR tyrosine kinase Gefitinib could suppress breast cancer metastasis induced by Akt1 inhibitor." (PMID 30445978, 2018). "Therefore, we sought to define the functional role of STAT1 downstream of EGFR activation in metastatic breast cancer cells." (PMID 30250119, 2018). "Indeed, in Akt1 impaired breast cancer cells, we also documented EGFR mediates β-catenin nuclear accumulation." (PMID 30445978, 2018). "Finally, anti-ANXA2 mAbs significantly inhibited EGF-induced proliferation and metastasis by successfully blocking of EGFR homo-dimerization, phosphorylation and internalization in breast cancer." (PMID 29568351, 2018). "However, therapies targeting EGFR in breast cancer have been met with many challenges and little success." (PMID 30367629, 2018). "However, EGFR-tyrosine kinase inhibitor (TKI) alone or in combination therapy with paclitaxel or docetaxel had been used for breast cancer patients in clinical trials, but both therapies failed." (PMID 30497501, 2018). "Foretinib induced caspase-dependent apoptosis in ovarian cancer and chronic myelogenous leukemia cell lines, while lapatinib was particularly effective in breast cancer cell lines – triple-negative as well as HER2-positive - and gefitinib in non-small lung cancer cells with mutated EGFR." (PMID 29719603, 2018). "Indeed, CDK4/6 inhibition was associated with a reduction in TSC2 phosphorylation in HER2-positive breast cancer mouse models and was shown to resensitize tumors to EGFR/HER2 blockade." (PMID 30167080, 2018).